MTOR (mechanistic target of rapamycin kinase)
Diseases named in the same sentence as MTOR in open-access papers (continued):
Sharing a sentence is not in itself a finding about the gene and the disease.
cancer (continued). "PTEN mutation and subsequent activation of PI3K/Akt signaling promotes the activation of mTOR signaling, which in turn promotes cancer cell survival, growth, cell cycle progression, angiogenesis, protein synthesis, and other cellular processes." (PMID 29515107, 2018). "As observed in cancer patients, we found that mTOR, a key signalling molecule responsible for maintaining cell growth and autophagy was suppressed in this model." (PMID 29618792, 2018). "A plethora of studies have shown that the AKT/mTOR molecules are promising therapeutical targets for cancers." (PMID 29997504, 2018). "Here, we review current knowledge of mTOR signaling, describe its cross-talk with other pathways, and examine its contribution to human cancer and potential for therapeutic targeting." (PMID 29351204, 2018). "The regulation of HIF1α and PKM2 expression by mTOR highlights the importance of mTOR signaling in regulation of cancer metabolism." (PMID 29844464, 2018). "It is well known that aberrant metabolism is one of the hallmarks of cancer; and increased glycolysis and lipogenesis are the major metabolic events downstream of mTOR." (PMID 29303510, 2018). "PI3K, along with downstream effectors such as AKT1 and mammalian target of rapamycin (mTOR), have been regarded as a possible target for cancer therapy." (PMID 29346447, 2018). "It has been reported that, aside from avoiding tumor immunity, PD-1/PD-L1 inhibition has also cancer cell-intrinsic functions that promote tumor growth and survival such as mTOR signaling." (PMID 30399174, 2018). "Non-transformed cells respond to this low nutrient state by downregulating mTOR activity and entering a state of quiescence, which can protect them from some chemotherapies; however, cancer cells often exhibit constitutive activation of PI3K/Akt/mTOR." (PMID 30410754, 2018). "Loss of contact inhibition is a hallmark of cancer and is commonly associated with disruption of PI3K/AKT/mTOR signalling and desmosomes." (PMID 29743597, 2018). "Activation of the mTOR signaling pathways results in deregulated protein synthesis and energy metabolism in many cancers." (PMID 30619768, 2018). "This study illustrates that the expression of GOPLH3 is pivotal in HCC by activating mTOR signaling pathway, which has emerged as an attractive therapeutic target for cancer therapy." (PMID 29914442, 2018). "In this study, we have analyzed the RCTs of PI3K/AKT/mTOR pathway inhibitors to assess their efficacy in all advanced solid cancers and whether they exhibit more efficient anti-tumour properties when combined with other targeted regimens or in cancers with PI3K mutations." (PMID 29408858, 2018). "Impairment of mTOR signaling by hypoxia (similarly to treatment with mTOR inhibitors) interfered with the senescence response of HPV-positive cancer cells against pro-senescent chemotherapeutic agents." (PMID 29637045, 2018). "There are numerous studies of the inhibition of PKB proteins and those present in the PI3K/AKT/mTOR signaling pathway, in order to control malignant cells and find better therapeutic alternatives for different types of cancer." (PMID 30544836, 2018). "Functional analyses in human cells and the zebrafish model indicate Ubtor inhibits mTOR signaling by stabilizing the mTOR complex component DEPTOR, and ubtor gene disruption resulted in higher mTOR activity and aggravated cancer formation in the zebrafish." (PMID 30080879, 2018). "The PI3K/AKT/mTOR signaling pathway, which is frequently abnormal in many tumor cells, is becoming an important target in cancer therapy." (PMID 29614812, 2018). "Gene amplification of growth factor tyrosine kinase receptors that are upstream of both PI3K and RAS are also common occurrences in cancer that also leads to aberrant signal transduction through both mTOR complexes." (PMID 29301334, 2018).
cancer (continued). "Oncogenic signal transduction through mTOR is a common occurrence in cancer, leading to metabolic transformation, enhanced proliferative drive and increased metastatic potential through neovascularisation." (PMID 29301334, 2018). "mTOR's implication in cancer stem cell proliferation has been demonstrated in various cancer types, such as colon, pancreas, or breast cancer." (PMID 30186236, 2018). "mTOR signaling is one of the major pathways in the management of autophagy, and the implications of mTOR signaling in cancer have been thoroughly investigated over the last decade." (PMID 30393233, 2018). "Metabolic reprogramming, mainly driven by deregulation of the nutrient‐sensing pathways as AMPK, mTOR and PI3K/AKT, has been associated with cancer cells, including AML cells, survival and proliferation." (PMID 30117681, 2018). "mTOR, as a therapeutic target against cancer, plays a pivotal role in cellular proliferation, growth, and survival." (PMID 30108651, 2018). "Current studies are also elucidating the mechanisms of cancer stem cells (CSCs) in replenishing tumors and explicating the strong correlation between the Akt/mTOR pathway and CSC biology." (PMID 30323898, 2018). "It is well established that PI3K/AKT/mTOR pathway is emerging as important player in the regulation of autophagy in various types of cancers." (PMID 29487530, 2018). "In this review, we summarize the current understanding we possess of the activation and role of PI3K/Akt/mTOR, downstream of Met, in cancer." (PMID 30406111, 2018). "Over the last decade, it has been widely demonstrated that the mTOR pathway is physiologically activated during various cellular processes and that it is deregulated in human diseases such as cancer." (PMID 30110936, 2018). "The role of the mammalian target of rapamycin (mTOR) complex in autocrine effects of Sema3A that promote cancer formation and help regulate disposal of senescent cells with DNA damage remains to be explored." (PMID 29854302, 2018). "PI3K/AKT/mTOR signaling pathway has been demonstrated to play an important role in regulating autophagy in cancer cells." (PMID 30153855, 2018). "mTOR inhibitors such as rapamycin and its analogs temsirolimus and everolimus are clinically approved treatments for several types of cancers." (PMID 29128895, 2018). "The mTOR and dual PI3K/mTOR inhibitors have been shown to induce Tregs’ expansion and their immunosuppressive activity, thus correlating with a poor prognosis in cancer patients." (PMID 30126252, 2018). "While mTOR is necessary for normal human physiology, cancer cells take advantage of mTOR signalling to drive their neoplastic growth and progression." (PMID 29301334, 2018). "Studies in cancer cells have shown that radiation induces mTOR signaling and that inhibition of mTOR alters cell cycle progression, apoptosis and repair to increase radiosensitivity." (PMID 29518028, 2018). "PD-L1 expression on cancer cells is associated with cancer cell-intrinsic signaling via the PI3K/Akt pathway and mTOR, leading to upregulation of glycolysis genes and enhanced glycolysis." (PMID 30123774, 2018). "While PARP inhibitors and PI3K/AKT/mTOR inhibitors are effective when tested as single agents, cancers almost invariably develop resistance to these drugs through multiple mechanisms and find alternate ways to grow." (PMID 30038706, 2018). "The ability of NVP-BEZ235 (dactolisib), a dual PI3K/mTOR inhibitor, to treat some cancer types is being evaluated in phase I/II clinical trials." (PMID 30423811, 2018). "In the past few years several investigations have focused on the role of PI3K/AKT/mTOR pathway and its deregulations in different cancers." (PMID 29383014, 2018). "mTOR is aberrantly activated in up to 80% of human cancers, and it up-regulates the translation machinery of proteins that are important for cancer cell growth, survival, invasion, and metastasis." (PMID 30041429, 2018).
cancer (continued). "Moreover, it has been suggested that metformin functions as an anticancer agent, predominantly via mTOR pathway inhibition; thus, its administration has been reported to be associated with improved survival in the treatment of patients with diabetes plus several types of cancers." (PMID 29565815, 2018). "The overall positive role of the PI3K/AKT/mTOR signaling pathway in cell growth and survival makes the rational for the therapeutic targeting of PTEN-deficient cancers with PI3K, AKT, or mTOR small molecule inhibitors." (PMID 29385737, 2018). "The insulin/IGF/mTOR system has been shown to play a key role in CRC development due to its complex involvement in the cancer’s cellular metabolism, proliferation, and differentiation." (PMID 30257507, 2018). "The activation of the mTOR pathway plays a key role in the development of several cancer types because of its importance in controlling cell growth and metabolism." (PMID 29932116, 2018). "TXNIP appears to be at the crossroads of various signaling molecules implicated in tumorigenesis and anti-cancer treatment, such as Myc, AMPK, and mTOR, making its regulation subject to diverse cellular processes." (PMID 29534438, 2018). "The activation of mTOR is related to many diseases such as cancer, cardiovascular diseases, neurodegenerative diseases as well as brain diseases; at the same time, inhibition of mTOR induces autophagy." (PMID 30174640, 2018). "Hyperactivation of the mTOR pathway increases cell growth and proliferation and stimulates tumor growth, representing a potential therapeutic target of cancers." (PMID 29665298, 2018). "Components of this pathway are frequently deregulated in an extensive number of tumors, making PI3K/AKT/mTOR signaling pathway an attractive target for cancer therapy." (PMID 30390677, 2018). "Like cancer cells, mTOR seems to play an important role in increasing proliferation in various types of fibroblasts." (PMID 29518028, 2018). "Promising preclinical studies using mTOR inhibitors have demonstrated efficacy in many human cancer types, including T-ALL." (PMID 29949919, 2018). "Understanding PI3K/Akt/ mammalian target of rapamycin (mTOR) signaling pathways, and the development of clinically useful inhibitors remain an active area of cancer research." (PMID 29973512, 2018). "Niclosamide confers multiple therapeutic effects for the treatment of cancers, infections, and metabolic diseases by interfering activation of the mTOR, STAT3, and NF-κB signaling pathways." (PMID 30125275, 2018). "Such transient or tumour-targeted mTOR inhibition would need to be investigated in additional immune-competent cancer animal models to determine the correct dosing and its potential therapeutic efficacy in combination with oncolytic HSV1." (PMID 30138450, 2018). "Rapamycin, an antifungal agent with immunosuppressive properties, was the first mTOR inhibitor developed for anti-cancer activity in the 90s." (PMID 29351204, 2018). "On the one hand, OA induces protective autophagy via MAPK8 and mechanistic target of rapamycin (mTOR) pathway activation in various cancer cells." (PMID 29636527, 2018). "Aberrations in various upstream regulators of the mTOR signaling pathway leading to its upregulation are frequently noted in cancers, providing rationale for inhibition of the mTORC1 signaling pathway." (PMID 29128895, 2018). "Oncogenic activation of mTOR signaling significantly contributes to the progression of different types of cancers including OS." (PMID 29921292, 2018). "It has been widely accepted that PI3K/AKT/mTOR pathway is a promising therapeutic target for the treatment of cancer." (PMID 29716528, 2018). "mTOR has been shown to play an important role in cell proliferation, metabolism, and tumor development, and proteins that modulate signals through mTOR are frequently changed in human cancers." (PMID 30393233, 2018).
cancer (continued). "Activating mutations of PI3K, AKT, mTOR as well as inactivating mutations of TSC1, TSC2 or PTEN are commonly observed in several types of cancers." (PMID 30061533, 2018). "Akt activation promotes metastasis and invasion of cancer cells, and phosphorylates mammalian target of rapamycin (mTOR)." (PMID 30390677, 2018). "The PI3K/Akt/mTOR signaling controls most hallmarks of cancer: cell cycle, survival, metabolism, motility, and genomic instability." (PMID 30619121, 2018). "The PI3K/AKT/mTOR pathway plays a key role in the promotion of cell survival and proliferation in cancers, and elevated PI3K pathway signalling seems to be a hallmark of cancer." (PMID 29408858, 2018). "RAC1 has previously been linked to PI3K/AKT/MTOR and RAF/MEK/ERK signalling and both these pathways can be important mechanisms of cancer cell evasion of apoptosis." (PMID 29329780, 2018). "mTOR also serve as a master regulator that senses amino acid availability to regulate cell growth in normal and cancer cells." (PMID 30105018, 2018). "Presence of AREG, p-EGFR, p-AKT and p-mTOR was confirmed in the cancer tissue, CRC cells and xenografts by immunohistochemistry (IHC)." (PMID 29419396, 2018). "Alterations in the PI3K/AKT/mTOR pathway occur in 38% of all cancers as demonstrated on nearly 20,000 tumors of diverse origins." (PMID 29506489, 2018). "Further, the deregulation of many signaling pathways such as EGF/RAS/RAF/MEK/ERK and PI3K/AKT/mTOR is considered to play a critical role in oncogenesis and cancer progression." (PMID 30127774, 2018). "Of interest, activated mTORC1 increased the level of ROS, suggesting that mTOR complex induces metabolic reprogramming via ROS production in response to unpreferable environments for cancer cells." (PMID 30347859, 2018). "The phosphoinositide 3-kinase/serine–threonine protein kinase AKT/mammalian target of rapamycin (PI3K/AKT/mTOR) signalling pathway is frequently deregulated in human cancer and is therefore a promising target for the development of new therapies." (PMID 29541803, 2018). "The network model successfully captures the key role of the PI3K/AKT/mTOR signaling pathway in determining the pathological proliferation and survival of cancer cells." (PMID 29867523, 2018). "PD-L1 inhibits autophagy through activation of MTOR, while the PD-L1 inhibitor attenuates autophagy for cancer cell survival." (PMID 30477228, 2018). "Due to the frequent activation of the PI3K/Akt/mTOR pathway in human cancers, more than 50 inhibiting drugs are in development, and several clinical trials are ongoing." (PMID 30363988, 2018). "In our study, the inhibitory effects of palbociclib on glucose metabolism were further enhanced by the combination with PI3K/mTOR inhibitors, being the AKT/mTOR signaling another key player in cancer metabolic reprogramming." (PMID 29587820, 2018). "Regulating PI3K/AKT/mTOR pathway in cancer cells will be a key aspect to make cancer cell viable for cell death elimination using chemotherapeutic drugs which are nontoxic to normal cells." (PMID 30096805, 2018). "It is well established that the integrin β4 and α6 complex induces c-Src signalling and mTOR activation which is important for stimulating transcription and translation of cancer related genes." (PMID 29526452, 2018). "Even though RapaLink-1 is still at the pre-clinical stage, RapaLink-1 holds much promise in the treatment of mTOR-hyperactive cancers." (PMID 29301334, 2018). "FBXO17 expression appears to be advantageous for tumor cell survival, and we propose that upregulation of Akt activation by this F-box protein is a potential mechanism for increased mTOR activation in cancer." (PMID 30359271, 2018).
cancer (continued). "They represent a major shift in our understanding of the prosurvival role of the mTOR complexes and highlight mitochondria-mediated ROS as a prosurvival autophagy regulator during cancer development." (PMID 30038268, 2018). "Molecular damage is essential for most types of cancer, but a senescent microenvironment and overall organism aging (and associated diseases such as diabetes) also play roles, as does clonal selection for mTOR activation in cancer cells." (PMID 30594910, 2018). "The PI3K/Akt/mTOR pathway governs the growth of cancer cells and has been the subject of intense interest in cancer therapy." (PMID 30546837, 2018). "The VEGF-C is involved in the activation of autophagy in cancer cells promoting their survival, probably through inhibition of the mammalian target of rapamycin (mTOR) complex 1 activity." (PMID 30573851, 2018). "The second generation of ATP-competitive mTOR inhibitors that target both mTORC1 and mTORC2 has shown greater effectiveness than rapalogs for cancer treatment." (PMID 29455662, 2018). "By contrast, inhibition of the H+-ATP synthase by α-ketoglutarate and the oncometabolite 2-hydroxyglutarate, reduces mTOR signaling, suppresses cancer cell growth, and contributes to lifespan extension in several model organisms." (PMID 29564224, 2018). "The PI3K/AKT/mTOR signaling pathway has been demonstrated to be highly involved in a variety of cancer types by contributing to the regulation of a series of cellular mechanisms, including proliferation, angiogenesis, metastasis and survival." (PMID 30349421, 2018). "One such central signaling center of cancer development is the phosphoinositide 3-kinase-AKT-mammalian target of rapamycin (PI3K/AKT/mTOR) pathway which plays a key role in cell survival, growth, and metabolism." (PMID 29951132, 2018). "As a result of the importance of the PI3K/AKT/mTOR pathway in cancer progression, targeting this signaling pathway has become one of the most studied strategies." (PMID 29932116, 2018). "In particular, PI3K/Akt/mTOR pathway modulates cell proliferation, survival, motility, invasion allowing cancer initiation and progression." (PMID 30546834, 2018). "mTOR inhibitors emerged in 1999 and were identified as protective agents against cancer (Faivre, Kroemer & Raymond, 2006; Wander, Hennessy & Slingerland, 2011)." (PMID 30473931, 2018). "In this article, we depict the recent findings on the role of mTOR complexes in cancer as a master regulator of cancer metabolism and a potential sensor of nutrients, especially focusing on glucose and amino acid sensing in cancer." (PMID 30347859, 2018). "We also noted that 4E-BP1 phosphorylation has been shown to correlate with primary resistance to mTOR inhibition in a variety of cancer cell lines." (PMID 29389967, 2018). "The link between the metabolism suppression and aggressiveness features of cancer cells remains poorly understood since anti-mTOR agents who are part of the repertoire of drugs used for systemic treatment of cancer achieving variable results." (PMID 29707520, 2018). "An example is the everolimus, an mTOR inhibitor approved by the FDA for the treatment of many types of cancer, including kidney cancer and some neuroendocrine tumors." (PMID 29455659, 2018). "PINK1 interacts with the pivotal oncogenic PI3K/Akt/mTOR signaling axis, mediating the critical mitochondrial and metabolic functions that regulate cancer survival, growth, stress resistance, and the cell cycle." (PMID 30595797, 2018). "MYC and FoxO are known in cancer metabolic adaptation and reprogramming, and the regulation of this axis is connected with the Akt/mTOR signaling pathway." (PMID 30515268, 2018). "Amongst the numerous pathways implicated in cancer development, the PI3K/Akt/mTOR signaling pathway is hyper-activated in cancer cells, which leads to cell survival and tumor proliferation." (PMID 30258193, 2018).